BDNF (brain derived neurotrophic factor)
Diseases named in the same sentence as BDNF in open-access papers (continued):
Sharing a sentence is not in itself a finding about the gene and the disease.
psychiatric disorder (continued). "Although the effect of BDNF in each psychiatric regulation is highly network-dependent, the ectopic expression of BDNF might be applicable for the treatment of cardiac disorders with psychiatric diseases." (PMID 34827728, 2021). "Also, several correlations between BDNF and pathophysiology of brain and psychiatric diseases were found." (PMID 34220571, 2021). "The brain-derived neurotrophic factor (BDNF) gene is considered to be one of the candidate genes of psychiatric disorders, as it is widely expressed in the brain and plays a major role in neurogenesis, neuronal growth, maturation, survival, synaptic plasticity, and microarchitectural integrity." (PMID 35095581, 2021). "The BDNF pathway was assumed to play a role in several psychiatric disorders, including PTSD." (PMID 32894097, 2020). "Therefore, regulating endotoxemia-mediated corticosterone and BDNF expression can be useful for the treatment of psychiatric disorders." (PMID 32158447, 2020). "BDNF signaling can demonstrate a well-reported function in psychiatric disorders." (PMID 33103739, 2020). "BDNF codes for Brain-Derived Neurotrophic Factor, active in neurodevelopment and synaptic plasticity; the gene has been extensively studied in the context of psychiatric disorders." (PMID 33193575, 2020). "BDNF is a key molecule in the CNS, able to affect mood, behavior, learning, and memory and a reduced circulating level of this neurotrophin is related to the development of psychiatric disorders." (PMID 32120967, 2020). "Brain-derived neurotrophic factor (BDNF) is a member of the neurotrophin family of growth factors, which are key regulators of synaptogenesis, neuronal plasticity, and adult neurogenesis, creating potentially important links between stress and mental illness." (PMID 33162938, 2020). "In humans, BDNF is known to be a useful biomarker for several psychiatric disorders." (PMID 30117106, 2019). "Brain-derived neurotrophic factor (BDNF) plays an important role in the pathophysiology of HD, as well as other neurodegenerative and psychiatric disorders, and epigenetic alterations in the complex BDNF promoter have been associated with its deregulation in pathological conditions." (PMID 32038165, 2019). "The mechanistic connection of Prevotella with cortisol and psychiatric disorders may potentially be explained by the involvement of brain-derived neurotrophic factor (BDNF)." (PMID 31491976, 2019). "Accordingly, altered synthesis and/or activity of BDNF, which are key regulators of many mental disorders, may contribute to the development of these mental diseases in adolescence." (PMID 29867348, 2018). "Importantly, it has been demonstrated that dysfunction of the BDNF/TrkB system is involved in the onset of brain diseases, including neurodegenerative and psychiatric disorders." (PMID 30463271, 2018). "The upregulation of pCREB and BDNF in the hippocampus might be contribute to ameliorating psychiatric disorders; while downregulation of pCREB and BDNF in the intestines might be contribute to recovering the intestinal dysfunction." (PMID 29962949, 2018). "All this contradictory information may be due to the use of surrogate tissues (especially blood samples) and the inherently complex organization of the BDNF that masks its definitive role in the molecular pathology of complex mental illness." (PMID 28387726, 2017). "The concept of treating psychiatric diseases by interacting with BDNF signaling has major caveats." (PMID 28280960, 2017). "Some authors speculate that BDNF has apotential role in the pathology and treatment of numerous psychiatric disorders." (PMID 29299044, 2017). "This suggests that alterations of BDNF levels in human serum, as reported in studies dealing with psychiatric diseases, might reflect changes occurring in megakaryocytes and platelets." (PMID 28280960, 2017).
psychiatric disorder (continued). "Future studies should address the cortical (in particular PFC) expression of BDNF more thoroughly since it may be of importance for considering face validity of social isolation as a model for human mental illness." (PMID 28620285, 2017). "Thus, manipulating the BDNF pathways represents a viable approach to treating a variety of neurological and psychiatric disorders." (PMID 28824455, 2017). "Furthermore, the addition of a BDNF protein or elevation of BDNF by the Bdnf gene (human gene: BDNF; mouse gene: Bndf) delivery in animal models of neurological and psychiatric disorders improves memory formation and the survival of neuronal cells." (PMID 28272318, 2017). "In addition, serum BDNF levels increase significantly in patients with severe mental illness during inpatient treatment." (PMID 28212323, 2017). "Thus higher BDNF methylation levels should determine reduced expression of BDNF gene and reduced BDNF mRNA levels are widely observed in patients with psychiatric diseases." (PMID 28619017, 2017). "BDNF’s roles in neuronal processes during development and adulthood, support its potential role in the pathogenesis and treatment of both neurological and psychiatric disorders." (PMID 26973456, 2016). "In fact, BDNF exerts potent pro-survival and functional effects in models of neurological diseases such as Parkinson’s, Huntington’s, and Alzheimer’s diseases, as well as depression and other psychiatric disorders." (PMID 26973456, 2016). "We suggest that through further investigations, an unequivocal answer if the BDNF DNA methylation level is a suitable psychiatric disorder biomarker may be provided." (PMID 27267954, 2016). "In addition, further work to determine if changes in blood BDNF concentrations mediate clinical benefits, such as those on mood, cognition and other psychiatric disorders, would help to determine the usefulness of peripheral BDNF as a putative biomarker." (PMID 27658238, 2016). "Moreover, distinguishing the role of BDNF in suicidal behaviour from its role in mental illness is a key difficulty across studies." (PMID 26718989, 2015). "However, epigenetic changes in other candidate genes such as brain-derived neurotrophic factor (BDNF) and serotonin transporter are also implicated in early life stress (ELS) and susceptibility to adult psychiatric disorders." (PMID 26583053, 2015). "There are varying reports on the relationship between mental illness and BDNF." (PMID 26405456, 2015). "Additional studies are needed to examine whether BDNF can inform our understanding, treatment, and prevention of aforesaid psychiatric disorders." (PMID 26453695, 2015). "The final two studies of serum BDNF levels focused on specific psychiatric disorders." (PMID 26718989, 2015). "BDNF has been found to mirror the cognitive decline accompanying mental illnesses." (PMID 26405456, 2015). "Given that BDNF is released in an activity-dependent manner, BDNF may be a key factor in experience-dependent vulnerability to psychiatric disorders." (PMID 26257661, 2015). "Thus, those individuals with major mental illness with a history of mood medication often had BDNF and trkB−TK+ mRNA levels comparable to the control group, thus suggesting that this medication may be normalizing an underlying deficiency in BDNF and trkB−TK+ mRNA levels." (PMID 24802307, 2014). "This suggests that BDNF has the ability to cross the blood brain barrier and that peripheral BDNF may potentially be relevant for studying psychiatric diseases." (PMID 25226879, 2013). "For instance, the potential etiological role of the brain derived neurotrophic factor (BDNF) gene in psychiatric disorders and cognitive traits could reflect its central role in synaptic plasticity." (PMID 22539971, 2012).
psychiatric disorder (continued). "Future studies on BDNF in (neuro)psychiatric disorders should control for these characteristics." (PMID 21247257, 2012). "During development, the expression of NGF and BDNF has been localized to the hippocampus and prefrontal cortex, two regions which are well-studied sites of both developmental and adult synaptic plasticity and playing a key role in psychiatric disorders." (PMID 22474604, 2012). "Thus, impairment of BDNF mRNA sorting and processing is likely involved in the pathogenesis of specific neuronal diseases such as HD and other psychiatric disorders." (PMID 20507609, 2010). "Furthermore, BDNF provides trophic support to noradrenergic, dopaminergic and serotonergic neurons, among others, whose neurotransmitters are altered in many mental illnesses." (PMID 20573217, 2010). "Despite uncertainty about how well peripheral BDNF reflects brain BDNF, it is one of the most widely used markers of neuroplasticity in human studies and seems related to several known correlates of neuroplasticity, including psychiatric disease, stress, and exercise." (PMID 39613915, 2025). "While still not clinically validated, brain-derived neurotrophic factor (BDNF) appears to be a promising biomarker for the early diagnosis of various psychiatric disorders, as well as conditions that may predispose individuals to them." (PMID 40563747, 2025). "BDNF also impacts intracellular Ca2+ signaling in microglial cells, which may be important in regulating inflammatory responses and may contribute to the pathophysiology and treatment of psychiatric disorders." (PMID 40002459, 2025). "Both DED and psychiatric disorders are linked to chronic systemic inflammation, hypothalamic–pituitary–adrenal (HPA) axis dysregulation, oxidative stress, mitochondrial dysfunction, and reduced levels of neurotrophic factors like brain-derived neurotrophic factor (BDNF)." (PMID 41226736, 2025). "Moreover, we hypothesized that pBDNF levels and BDNF DNA methylation may correlate with the severity of psychiatric symptoms, potentially serving as biological markers of stress-related psychiatric disorders in occupational settings." (PMID 39595869, 2024). "While most of these missense polymorphisms were previously documented in databases like Variation Viewer and ClinVar, none had previously been linked to psychiatric disorders through either association studies or functional research, with the exception of rs6265 in the BDNF gene." (PMID 38699454, 2024). "Given these gaps in the literature, the rationale for our study was to explore whether BDNF levels and methylation patterns could differentiate between workers exposed to occupational stress and suffering from psychiatric disorders compared to healthy controls." (PMID 39595869, 2024). "Therefore, BDNF/TrkB signaling may serve as a valid target for ameliorating neurological and psychiatric disorders, including AD." (PMID 39274839, 2024). "Therefore, (antidepressant) treatment leading to an increase in brain BDNF levels might be helpful in the treatment of that mental disorder." (PMID 39194496, 2024). "Our central hypothesis was that workers experiencing significant occupational stress and presenting psychiatric disorders will exhibit altered plasma BDNF (pBDNF) levels and increased methylation of BDNF promoters, reflecting stress-related epigenetic regulation." (PMID 39595869, 2024). "The nonspecific association of BDNF methylation with psychiatric disorders and the discordance between the level of BDNF methylation and its protein may be due to other regulators of expression." (PMID 35853898, 2022). "Despite BDNF deficit, another candidate that may contribute to the observed antioxidant failure is the immune/inflammatory system, whose role in both stress response and psychiatric diseases is well recognized." (PMID 35459959, 2022).
psychiatric disorder (continued). "58-65 Although presence of psychiatric disorders could lead to changes in BDNF levels, no influence associated with such comorbidities was observed in our study." (PMID 34060728, 2022). "One of them is brain-derived neurotrophic factor (BDNF), a nerve growth factor commonly expressed in the central nervous system; the intensity of expression varies depending on the region as well as concomitant pathologies, e.g., psychiatric disorders or aging." (PMID 36294343, 2022). "Moreover, it remains unknown if it is clinically viable to target low BDNF levels in neurodegenerative or psychiatric disorders via gene therapy." (PMID 35887357, 2022). "Interestingly, the Nrf2 antioxidant pathway may be activated by the brain-derived neurotrophic factor (BDNF), one of the major mediators of neuroplasticity involved in stress response and stress-related psychiatric disorders." (PMID 35459959, 2022). "Importantly, BDNF modulates neural circuits that can, in turn, regulate dopaminergic, serotonergic and GABAergic systems, all neurochemical pathways putatively involved in the pathogenesis of psychiatric disorders." (PMID 36552127, 2022). "Interestingly, in animal models, it has already been established that BDNF can be the potential therapeutic target for psychiatric disorders and neurological disorders, even though the BDNF protein itself has a short half-life and can hardly penetrate the blood brain barrier." (PMID 34827728, 2021). "Considering the pivotal function of BDNF, it has been suggested that the BDNF Val66Met may have a role in the etiology of several neurological diseases and psychiatric disorders." (PMID 34025349, 2021). "Thus, abnormalities in the processing of BDNF and BDNF pro-peptide from proBDNF in the parietal cortex may contribute to the pathogenesis of major psychiatric disorders." (PMID 33627628, 2021). "Furthermore, various patient-specific variables such as comorbid psychiatric disorders and psychotropic medications might have also exaggerated the effect of BDNF Val66Met on memory bias and function in the PTSD group." (PMID 32081932, 2020). "Thus, manipulating the BDNF signaling may present a viable approach to treat a variety of neurological and psychiatric disorders." (PMID 33096634, 2020). "It is broadly involved in synapse maturation, synaptic plasticity, neurite outgrowth and arborization, and maintenance of normal cognitive function, while dysfunction of BDNF may contribute to the progression of multiple neurological diseases and psychiatric disorders." (PMID 32399020, 2020). "Considering the involvement of both BDNF and neuroinflammation in several psychiatric diseases and the diverse incidence of such pathologies in males and females, a deeper investigation of the mechanisms underlying their interaction may have a critical translational relevance." (PMID 31379496, 2019). "The overlapping regions within BDNF promoter I and promoter IV may be of special interest as possible biomarker of psychiatric diseases, taking into consideration that several independent studies reported about the differences in the methylation level of these regions." (PMID 29636708, 2018). "However, more attention has been given to BDNF because specifically interfering with BDNF-related signaling is a key strategy for initiating neuronal and functionally restorative treatments for neurological and psychiatric disorders." (PMID 29853837, 2018). "Furthermore, some authors have suggested that BDNF blood levels may serve as a biomarker for the diagnosis of neurodegenerative diseases and psychiatric disorders and can also serve as a surrogate marker for the success of therapies in these disorders." (PMID 30327610, 2018). "Expression of brain-derived neurotrophic factor (BDNF), which is important for normal development, survival, and plasticity of central nerve system neurons, is known to be altered in response to stress and is involved in the pathophysiology of psychiatric disorders." (PMID 28491024, 2017).
psychiatric disorder (continued). "Therefore, BDNF levels could be considered as a transdiagnostic marker for psychiatric disorder activity." (PMID 28212323, 2017). "Recent research indicates that BDNF may create an important link between stress and mental illness." (PMID 28620285, 2017). "These overlapping regions within BDNF promoter I and promoter IV may be of special interest as possible biomarker of psychiatric diseases, taking into consideration that several independent studies reported about the differences in the methylation level of these regions." (PMID 27267954, 2016). "Both Keller’s and our study covered only certain brain areas (frontal cortex, cerebellum, Wernicke area), while BDNF DNA methylation changes in such brain regions as hippocampus, nucleus accumbens, amygdala may be essential for psychiatric disorders development." (PMID 27267954, 2016). "Furthermore, since BDNF is significantly lower in individuals with psychiatric disorders, an increase in BDNF via exercise may confer clinical benefit by ameliorating this abnormality." (PMID 27658238, 2016). "Importantly, studies suggest that peripheral BDNF concentrations may reflect CNS health to some extent, with concentrations typically being lower in patients with psychiatric disorders and metabolic disorders." (PMID 27658238, 2016). "Therefore, together with findings as described in this review, it is possible that juvenile social experience-dependent myelination occurs through the expression of well-known risk molecules for psychiatric disorders, NRG1 and BDNF, and results in the development of psychiatric disorders." (PMID 26078885, 2015). "However, clinical investigations of BDNF in psychiatric disorders is contradictory." (PMID 26453695, 2015). "The differences found in the other three studies could have resulted from altered BDNF levels associated with psychiatric disorders rather than suicidal behaviour." (PMID 26718989, 2015). "However, more studies are needed to elucidate the possible mechanisms by which n-3 PUFAs intake affects BDNF levels, and how this may lead to an increased vulnerability to psychiatric disorders." (PMID 24593295, 2014). "Independent variables included several factors: BDNF, TrkB, CREB, gender, time of illness, marital status, age, BMI, smoking status, family history of mental illness, education level, P-score, N-score, and total PANSS score." (PMID 40534913, 2025). "Among the neurotrophic factors, preclinical data indicate a prominent role for brain-derived neurotrophic factor (BDNF) as a biomarker for stress vulnerability and psychiatric disorders." (PMID 40656087, 2024). "Recently, research has found a relationship between BDNF and GDNF and the occurrence of mental illness." (PMID 37509026, 2023). "The aim of the present study was to explore the associations between psychiatric symptoms as measured by of SCL-90-R with serum BDNF and hs-CRP levels in a patient sample admitted to open ward inpatient stay for treatment of psychiatric disorders." (PMID 35114967, 2022). "Meanwhile, potential shared molecular pathophysiology has been proposed between psychiatric disorders and FTD like brain derived neurotrophic factor (BDNF) and progranulin." (PMID 35509074, 2022). "In addition, since the modulation of BDNF levels is observed in other psychiatric conditions, the persistent AN-induced changes of the BDNF system in the amygdala might contribute to explaining the onset of comorbid psychiatric disorders that persist in patients even beyond recovery from AN." (PMID 36570702, 2022). "BDNF is broadly involved in synapse maturation, synaptic plasticity, the maintenance of normal cognitive function, and neurite outgrowth arborization, while BDNF dysfunction may contribute to the progression of multiple neurological diseases and psychiatric disorders." (PMID 35055089, 2022). "GSK3B, BDNF, NGF, NRG1, HTR2C, and PIP4K2A play important roles in molecular mechanisms of psychiatric disorders." (PMID 33193575, 2020).